TRIM2 (tripartite motif containing 2)
Diseases named in the same sentence as TRIM2 in open-access papers (continued):
Sharing a sentence is not in itself a finding about the gene and the disease.
melanoma (3 papers, 2020 to 2024). A malignant, usually aggressive tumor composed of atypical, neoplastic melanocytes. "TRIM2 was found to be highly expressed in melanoma, and this finding was verified by qRT–PCR, indicating that TRIM2 plays an important role in the occurrence and development of melanoma." (PMID 36051486, 2022). "Furthermore, the GEPIA database was used to analyze the prognostic value of TRIM2 in melanoma." (PMID 36051486, 2022). "However, the oncogenic role of TRIM2 in melanoma needs to be confirmed by further experiments in vivo and in vitro, and the oncogenic mechanism remains unclear." (PMID 36051486, 2022). "We used the GEPIA database to investigate the prognostic analysis of TRIM2, TRIM7, TRIM8, TRIM18 (MID1), TRIM19 (PML), TRIM27, and TRIM29 in melanoma." (PMID 33118318, 2020). "The gene expression of TRIM2 and TRIM27 was markedly higher, and the expression of TRIM7, TRIM8, and TRIM29 was significantly downregulated in melanoma." (PMID 33118318, 2020). "In the GEPIA database, TRIM2 and TRIM27 expression were significantly higher, and TRIM7 and TRIM29 expression was significantly downregulated in melanoma; these results were consistent with data from the Oncomine database (all p < 0.05)." (PMID 33118318, 2020). "Differential expression of TRIM2, TRIM7, TRIM8, TRIM18 (MID1), TRIM19 (PML), TRIM27, and TRIM29 may play an important role in the development of melanoma." (PMID 33118318, 2020).
neuroblastoma (3 papers, 2020 to 2025). Neuroblastoma (NB) is the most common solid, extracranial childhood tumor. "Upregulation of TRIM2 expression has recently been shown to promote the growth of neuroblastoma cells." (PMID 36051486, 2022). "The NR2F1-AS1/miR-493 axis was concluded to promote the progression of neuroblastoma by regulating TRIM2." (PMID 36051486, 2022). "As a downstream target gene, TRIM2 regulates the occurrence and development of neuroblastoma in cooperation with its upstream mediators, and the relationship between TRIM2 and miR-145 was verified by a dual luciferase reporter assay." (PMID 36051486, 2022). "Studies related to TRIM2 in tumors have primarily revealed that it plays a role in promoting tumor growth by fostering tumor proliferation, invasion, and migration, as shown in cancers such as neuroblastoma and pancreatic cancer." (PMID 36051486, 2022). "In neuroblastoma, NR2F1-AS1 enhances motility in SK-N-SH and SK-SY5Y cells through the miR-493-5p/TRIM2 axis." (PMID 40828427, 2025). "Neuroblastoma cells (SK-N-SH and SK-SY5Y) exhibit increased proliferation and reduced apoptosis upon NR2F1-AS1–mediated activation of TRIM2 via miR-493-5p." (PMID 40828427, 2025). "In addition, we tested by immunofluorescence using commercial antibodies whether endogenous TRIM2 and ALIX do show overlapping expression in a human neuroblastoma cell line SH-SY5Y." (PMID 32698497, 2020).
pancreatic cancer (3 papers, 2022). "TRIM2 silencing can significantly inhibit the proliferation, migration, invasion, and tumorigenicity of pancreatic cancer cells." (PMID 36051486, 2022). "In a previous study, TRIM2 was found to accelerate pancreatic cancer progression through the ROS-related NRF2/ITGB7/FAK axis, and excessive production of ROS has been considered to be the main mechanism of DMBA-mediated oral carcinogenesis." (PMID 36051486, 2022). "Research on the relationship between TRIM2 and pancreatic cancer revealed that the expression of TRIM2 in pancreatic cancer is significantly increased, which was negatively correlated with the prognosis of pancreatic cancer." (PMID 36051486, 2022). "TRIM2 also plays a role in cell cycle regulation in both pancreatic cancer and ccRCC." (PMID 36051486, 2022). "The level of ROS in pancreatic cancer cells was significantly decreased by TRIM2 knockdown, and the mechanism may involve the positive correlation of TRIM2 expression with NRF2 expression." (PMID 36051486, 2022). "TRIM2 may thus be a promising biomarker and therapeutic target in pancreatic cancer." (PMID 36051486, 2022). "In a further mechanistic study, it was concluded that TRIM2 can accelerate the progression of pancreatic cancer through the ROS-related NRF2/ITGB7/FAK axis, which reveals a new regulatory role of TRIM2 through the regulation of redox homeostasis and integration of independent signaling pathways." (PMID 36051486, 2022).
viral infection (3 papers, 2019 to 2022). "TRIM-2 knockdown experiments using JUNV or pseudo-typed retroviruses bearing JUNV’s GP on their surface revealed that TRIM-2 restricts viral infection at the entry stage, more specifically, at a post-binding step." (PMID 35746604, 2022). "A similar decrease in phosphorylation of endogenous SIRPA was seen after Tacaribe virus infection of TRIM2-transfected U2OS cells." (PMID 30726215, 2019). "Moreover, experiments using TRIM-2-knockout mice confirmed that TRIM-2 also suppresses viral infection in vivo." (PMID 35746604, 2022). "Expression changes in UPS genes identified in both ST_EPN_RELA and PF_EPN_B included several differentially expressed UPS genes associated with interferon gamma signaling (MID1, PIAS1, TRIM2, TRIM22, TRIM45) that may promote a proinflammatory milieu similar to that observed upon viral infections." (PMID 36293188, 2022).
Alzheimer disease (2 papers, 2019 to 2022). A progressive, neurodegenerative disease characterized by loss of function and death of nerve cells in several areas of the brain leading to loss of cognitive function such as memory and language. "Furthermore, increased expression of TRIM2 has been observed in Alzheimer’s disease as a consequence of a decrease in miRNAs able to downregulate TRIM2 mRNA21." (PMID 36481767, 2022).
cervical cancer (2 papers, 2020 to 2022). A primary or metastatic malignant neoplasm involving the cervix. "Due to the comparative lack of research findings, either TRIM2 does not play a role in cervical cancer or whether it plays a role needs further verification in vivo and in vitro." (PMID 36051486, 2022). "Notably, in a study of cervical cancer, no consistent difference in the expression of TRIM2 was found between cancer tissues and normal cervical squamous epithelium." (PMID 36051486, 2022).
hemorrhagic fever (2 papers, 2019 to 2022). An infectious disease caused by certain viruses or bacteria that can damage the walls of tiny blood vessels, making them leak, and can hamper the blood's ability to clot and cause severe, life-threatening illness. "In a relevant research, TRIM2 was found through in vivo experiments in mice to play a unique antiviral role by interacting with SIRPA to block cellular entry of hemorrhagic fever New World arenavirus (NWA)." (PMID 36051486, 2022). "Here, we found that TRIM2, which has been implicated in cases of Charcot–Marie–Tooth disease (CMTD) in humans, acts by blocking hemorrhagic fever New World arenavirus (NWA) entry into cells." (PMID 30726215, 2019).
idiopathic pulmonary fibrosis (2 papers, 2022 to 2024). Idiopathic pulmonary fibrosis (IPF) is a nonneoplastic pulmonary disease that is characterized by the formation of scar tissue within the lungs in the absence of any known cause. "By silencing the lncRNA DLEU2, the idiopathic pulmonary fibrosis was suppressed through upregulating miR-369-3p expression and downregulating TRIM2 expression." (PMID 35484171, 2022). "LncRNA DLEU2 targets miR-369-3p and reduces the inhibitory effect of miR-369-3p on E3 ubiquitin ligase TRIM2, thereby promoting EMT in lung fibrosis and aggravating lung fibrosis." (PMID 39113708, 2024).
invasive breast carcinoma (2 papers, 2020 to 2024). A carcinoma that infiltrates the breast parenchyma. "The gene expressions of ACOT7, STAT1, TYMP, and VOPP1 were significantly increased in invasive breast carcinoma, while the gene expressions of ACTG2, CNN1, CDC14B, NFIB, RCN1, and TRIM2 were dramatically downregulated in BRCA." (PMID 31986487, 2020).
kidney cancer (2 papers, 2020 to 2021). Primary or metastatic malignant neoplasm involving the kidney. "TRIM2 may inhibit the progression and metastasis of kidney cancer through ubiquitinated modification of cell adhesion molecules and Th17 differentiation key proteins." (PMID 33223511, 2020).
multiple sclerosis (2 papers, 2015 to 2016). A progressive autoimmune disorder affecting the central nervous system resulting in demyelination. "SNP rs12644284 located in TRIM2 moderately contributed to extreme MS in a European-descent population (OR = 2.04, allele “G”), and was found to be associated with RA in this study." (PMID 27812365, 2016). "Additionally, three were associated with neurological disorders or functions including SZ (rs4129585 at TSNARE1), multiple sclerosis (rs12644284 at TRIM2) and brain structure (rs12479254 at BOK)." (PMID 25990720, 2015).
neuropathies (2 papers, 2022 to 2023). "A compound heterozygous mutation in the TRIM2 gene was found in a patient with early-onset neuropathy, and abnormal accumulation of axonal neurofilaments caused by a lack of ubiquitin in TRIM2 may be the potential mechanism of its pathogenesis." (PMID 36051486, 2022).
ovarian carcinoma (2 papers, 2022 to 2024). A malignant neoplasm originating from the surface ovarian epithelium. "In a study to evaluate ovarian cancer progression, high TRIM2 expression promoted proliferation and invasion in ovarian cancer cells." (PMID 38893070, 2024). "In a study on ovarian cancer progression, high TRIM2 expression was found to promote the proliferation and invasion of ovarian cancer cells." (PMID 36051486, 2022). "In another study, related gene sequencing experiments confirmed that the expression of miR-145 in ovarian cancer tissues and cell lines was consistently downregulated compared with that in normal ovarian tissues and further confirmed that TRIM2 was the downstream target gene of miR-145." (PMID 36051486, 2022).
autism spectrum disorder (1 paper, 2020). A spectrum of developmental disorders that includes autism, and Asperger syndrome. "HECTD1, like TRIM2, is an E3-ubiquitin ligase, with mutations implicated in autism spectrum disorders and neurodegeneration." (PMID 32233732, 2020).
Buccal Mucosa Cancer (1 paper, 2022). "TRIM2 was found to be consistently expressed at low levels in buccal mucosa cancer." (PMID 36051486, 2022). "However, no relevant in vivo and in vitro experimental studies have been conducted, and it is necessary to further confirm the role of TRIM2 in the occurrence and development of buccal mucosa cancer and to explore the related mechanism." (PMID 36051486, 2022).
dementia (1 paper, 2025). Loss of intellectual abilities interfering with an individual's social and occupational functions. "Our pharmacogenomic analysis identifies TRIM2, FBXO44, and GLTPD2 as potential genetic modifiers, whose higher expression levels attenuate the deleterious effects of N06AX antidepressants on WMH burden, with GLTPD2 also reducing dementia risk." (PMID 40799764, 2025).
fibrosis (1 paper, 2025). the formation of excess fibrous connective tissue in an organ or tissue in a reparative or reactive process. "Interaction between Dle2 and TRIM2 with miR-369-3p, which TRIM2 regulates, was observed to increase in lung tissue from mice with BLM-induced fibrosis and in TGF-β1-stimulated A549 cells, where miR-369-3p levels were reduced." (PMID 40901482, 2025).
Motor axonal neuropathy (1 paper, 2021). Progressive impairment of function of motor axons with muscle weakness, atrophy, and cramps. "TRIM2 encodes a ubiquitin ligase that targets the large neurofilament, and TRIM2 recessive loss-of-function mutations have been found to be causative for hereditary motor axonal neuropathy." (PMID 34290090, 2021).
neuritis (1 paper, 2012). A neuropathy arising from inflammation of one or more nerves. "Also, genes involved in nervous system development were found, for example ATP1B1 (involved in aggregation of neurons), TRIM2 (neuroprotection of cortical neurons) and VAPA, SGK1 and ZFYVE27 (involved in morphogenesis of neuritis)." (PMID 23028713, 2012).
oral cancer (1 paper, 2024). "However, differential expression was observed with TRIM2, ADD3, and ABCE1 among some of the oral cancer cell lines." (PMID 38396844, 2024).
rectal cancer (1 paper, 2020). A primary or metastatic malignant neoplasm that affects the rectum. "It was notable that upregulation of TRIM2 expression in rectal cancer can promote metastasis of rectal cancer cells through epithelial-mesenchymal transition." (PMID 32536816, 2020).
renal carcinoma (1 paper, 2020). A carcinoma arising from the epithelium of the renal parenchyma or the renal pelvis. "Previous studies predict that TRIM2 may inhibit the proliferation and metastasis of renal cancer by degrading HIF-α." (PMID 32536816, 2020).
renal cell carcinoma (1 paper, 2020). "Hence, TRIM2 may serve as a potential target to inhibit the progression and metastasis of renal cell carcinoma." (PMID 33223511, 2020).
thyroid follicular carcinoma (1 paper, 2022). "TRIM2 is abnormally expressed in thyroid follicular carcinoma." (PMID 36051486, 2022).
Vocal cord paralysis (1 paper, 2022). A loss of the ability to move the vocal folds. "Subsequent exon sequencing of a patient with early onset of CMT and bilateral vocal cord paralysis revealed a homozygous TRIM2 mutation; this mutation was embedded in an 18 Mb homozygous region, which may lead to vocal cord paralysis." (PMID 36051486, 2022).
tumor (17 papers, 2020 to 2025). "In CRC, EPI promotes tumor progression and M2 polarization of tumor‐associated macrophages (TAMs) through regulation of the TRIM2‐NF‐κB pathway." (PMID 41415714, 2025). "TRIM2 also displayed a curious association with low tumour grade (p < 0.0001), while remaining unrelated to other clinicopathological parameters including tumour size, nodal stage, and HER2 status." (PMID 38893070, 2024). "Studies have shown that TRIM2 can be defined as a potential biomarker to evaluate tumor for diagnostic and prognostic evaluation in cancers." (PMID 36051486, 2022). "Previous studies have implicated that TRIM2 plays roles in a variety of physiological and pathological processes, including neuronal rapid ischemic tolerance, antiviral responses, neurological diseases, tumor proliferation, migration, invasion, and apoptosis." (PMID 40883557, 2025). "Even when accounting for established prognostic factors such as tumour size, tumour grade, and lymph node stage, high TRIM2 mRNA expression remained a powerful predictor of BCSS (p < 0.01), reinforcing its potential as an independent prognostic marker." (PMID 38893070, 2024). "TRIM2 is considered an oncogene, as it is highly expressed in many cancers and related to tumour cell proliferation, apoptosis, metastasis, and angiogenesis." (PMID 38893070, 2024). "While no overall association was observed, high TRIM2 levels were significantly linked to worse OS in TNBC and ER-negative tumours (both p < 0.05)." (PMID 38893070, 2024). "Further statistical analysis of the TCGA-kidney renal clear cell carcinoma (KIRC) dataset showed that TRIM2 expression was significantly correlated with tumor recurrence, OS, and DFS." (PMID 36051486, 2022). "TRIM2 promotes tumor growth and metastasis by promoting angiogenesis and regulating the immune microenvironment or inhibiting tumor growth." (PMID 36051486, 2022). "miR-222–5p has been reported to highly expressed in ccRCC tumor cells and repress the express of TRIM2 and thus promote the progression and prognosis of metastatic ccRCC." (PMID 36090028, 2022). "The expression of TRIM2 in tumor tissue was slightly lower than that in adjacent tissue, but the difference was nonsignificant." (PMID 36051486, 2022). "TRIM2 plays a role in regulating tumor progression and is related to various signaling pathways, proteins, and miRNAs." (PMID 36051486, 2022). "Immunohistochemical analysis showed that TRIM2 was highly expressed in tumor tissues in a study of TRIM2 in CRC that also included in vitro cell proliferation assays, cell adhesion assays, and Transwell migration and invasion assays." (PMID 36051486, 2022). "The m6A level of AKAP12 was significantly down-regulated in the tumor by 8.88-fold and conversely that of TRIM2 was significantly up-regulated by 2.38-fold." (PMID 36303829, 2022). "In the tumor stage, metastasis stage, pathological stage and grade, we found that TRIM2 decreased significantly (all p values < 0.05)." (PMID 33223511, 2020). "In tumor tissues, the relative mRNA expression levels of hsa_circ_0002286, hsa_circ_0000512 and TRIM2 were lower than those in normal tissues (P < 0.01), while the expression levels of hsa-mir-222-5p was significantly increased in tumor tissues (P < 0.01)." (PMID 33223511, 2020). "Interestingly, the opposite trend emerged in ER-positive tumours, where high TRIM2 mRNA correlated with longer OS (p < 0.0001)." (PMID 38893070, 2024). "In vivo xenograft mouse model studies could determine the upregulation effects of TRIM2 involved in tumour growth." (PMID 38893070, 2024). "However, in other studies, including studies in ccRCC, FTC, and oral buccal mucosa cancer, TRIM2 has been shown to act as a tumor suppressor." (PMID 36051486, 2022). "Some studies have suggested that TRIM2 is related to tumor stage and patient age." (PMID 36051486, 2022).
tumor (continued). "Ultimately, a core tumor suppressor axis (circRNA_0002286 / miR-222-5p / TRIM2) was identified." (PMID 33223511, 2020). "Additionally, the relative mRNA expression levels of hsa_circ_0002286, hsa_circ_0000512, hsa_circ_0003596, hsa_circ_0035436, hsa-mir-222-5p and TRIM2 were markedly different between tumor cell lines and 293T cell line (P <0.05)." (PMID 33223511, 2020). "Thus, we speculated that TRIM2 may also ubiquitinate Bim and activate the ER stress response, which may play a role in promoting tumor progression or regulating tumor autophagy and become a potential therapeutic target in cancer." (PMID 36051486, 2022). "In addition, whether TRIM2 can be a biological target for targeted treatment of abnormal tumor angiogenesis and whether any potential signaling pathways related to TRIM2 could be exploited for this purpose must be investigated." (PMID 36051486, 2022). "However, the role of TRIM1 remains unclear, whereas TRIM2 plays dual roles by acting as an oncogene or as a tumor suppressor." (PMID 35371994, 2022). "TRIM2 held predictive power for DMFS in all patients receiving chemotherapy (p < 0.05), particularly in TNBC (p < 0.05) and ER-negative tumours (p < 0.01)." (PMID 38893070, 2024). "Therefore, in-depth research on the involvement of TRIM2 in EMT is worthwhile, which will be helpful for tumor diagnosis, treatment, and prognosis." (PMID 36051486, 2022). "Moreover, the expression of TRIM2 was significantly correlated with tumor stage and age but not with sex, body weight, tumor size, tumor differentiation, or preoperative CEA level." (PMID 36051486, 2022). "However, TRIM2 is not the only TRIM protein that plays a regulatory role in tumor cells." (PMID 36051486, 2022). "In both TNBC and ER-negative tumours, high TRIM2 protein retained its predictive power for BCSS, DFS, and DMFS, remaining independent of established prognostic factors, namely, tumour size, tumour grade, and lymph node stage (p < 0.05)." (PMID 38893070, 2024).